TNS4 (tensin 4)
Description:
Promotes EGF-induced cell migration by displacing tensin TNS3 from the cytoplasmic tail of integrin ITGB1 which results in dissociation of TNS3 from focal adhesions, disassembly of actin stress fibers and initiation of cell migration. Suppresses ligand-induced degradation of EGFR by reducing EGFR ubiquitination in the presence of EGF. Increases MET protein stability by inhibiting MET endocytosis and subsequent lysosomal degradation which leads to increased cell survival, proliferation and migration.
Synonyms: CTEN; PP14434
Tractability: Antibody: UniProt predicts a signal peptide or a membrane-spanning region. PROTAC: ubiquitination databases record sites on it.
Gene: Protein-coding gene on chromosome 17 (40,475,828 to 40,501,627, reverse strand). Ensembl gene ENSG00000131746.
Subcellular location: Cell junction, focal adhesion; Cytoplasm, cytoskeleton
Subcellular location (Human Protein Atlas): Cytosol
Pathways (Reactome):
Signal Transduction: MET interacts with TNS proteins
Gene Ontology:
Molecular function: protein binding
Biological process: intracellular protein localization
Cellular component: cytosol; focal adhesion; cytoskeleton
Genetic constraint (gnomAD): Loss-of-function variants: 46 observed, 70.08 expected, observed/expected ratio (o/e) 0.66, 90% interval 0.52 to 0.84. The upper end of that interval is the gene's LOEUF score, 0.84, which puts it in group 3 of 6, group 1 being the genes least tolerant of losing a copy. Missense variants: 863 observed, 928.88 expected, observed/expected ratio (o/e) 0.93, 90% interval 0.88 to 0.98. Synonymous variants: 390 observed, 375.08 expected, observed/expected ratio (o/e) 1.04, 90% interval 0.96 to 1.13.
Homologues: Orthologues: chimpanzee TNS4 (99% identical), macaque TNS4 (95% identical), dog TNS4 (84% identical), pig TNS4 (83% identical), rabbit TNS4 (78% identical), mouse Tns4 (75% identical), guinea pig TNS4 (74% identical), rat Tns4 (73% identical), tropical clawed frog tns4 (41% identical), Caenorhabditis elegans shc-2 (15% identical), Drosophila melanogaster Egfrap (12% identical), Drosophila melanogaster PVRAP (11% identical). Paralogues in human: TNS2 (32% identical).
Diseases named in the same sentence as TNS4 in open-access papers:
TNS4 is named in the same sentence as 52 diseases in open-access papers, as found by Europe PMC text mining. Sharing a sentence is not in itself a finding about the gene and the disease. The quoted sentences say what the papers report.
gastric cancer (12 papers, 2017 to 2025). A primary or metastatic malignant neoplasm involving the stomach. "High expression of TNS4 was reported to be associated with poor prognosis in gastric cancer and esophageal squamous cell carcinoma patients." (PMID 35807355, 2022). "High expression of TNS4 is associated with a poor prognosis in many cancer types, such as gastric cancer and lung adenocarcinoma." (PMID 32188434, 2020). "In gastric cancer, TNS4 contributes to disease progression by upregulating p-AKT, p-GSK-3β, and β-catenin." (PMID 39995671, 2025). "According to one study, increased TNS4 expression leads to poor treatment outcomes in gastric cancer patients." (PMID 36245988, 2022). "TNS4 is overexpressed in many types of cancer, such as colorectal cancer, gastric cancer and hepatocellular cancer, and plays an oncogenic role in carcinogenesis." (PMID 32732965, 2020). "Furthermore, TNS4 was associated with the prognosis of LUAD, and it served an important role in the migration and invasion of gastric cancer." (PMID 36793937, 2023). "There is frequent over-expression of TNS4 in gastric cancer showing the biologically aggressive behavior with its high expression, so high TNS4 mRNA expression may be a novel prognostic predictor for gastric cancer patients." (PMID 29283424, 2017). "Recent studies indicate that aberrant TNS4 expression is involved in various malignancies, such as breast carcinoma, lung cancer, colorectal cancer (CRC), and gastric cancer 12-16." (PMID 38164166, 2024). "Tensin-4 (or TNS4) functions as an oncogene and promotes cell proliferation and/or motility in numerous solid tumors, including pancreatic cancer, gastric cancer, hepatocellular carcinoma, and colorectal cancers." (PMID 30965637, 2019).
lung adenocarcinoma (12 papers, 2018 to 2025). A carcinoma that arises from the lung and is characterized by the presence of malignant glandular epithelial cells. "In lung adenocarcinoma cells, TNS4 induces TGF-β1 expression to promote EMT." (PMID 40906372, 2025). "The intersections of LPS induction-related genes, lung adenocarcinoma differential genes, and univariate cox genes were obtained, and five genes (TNS4, PRC1, MKI67, CDKN3, BIRC5) were obtained, which were defined as the characteristic genes associated with LPS induction." (PMID 40697537, 2025). "Furthermore, ANXA8L1 (kidney renal papillary cell carcinoma), CYP4B1 (lung adenocarcinoma) and TNS4 (stomach adenocarcinoma) showed a significant relation with survival in these cancers." (PMID 35807355, 2022). "Similarly, expression of TNS4 was downregulated by miR-150-3p to suppress lung adenocarcinoma cell development." (PMID 33958701, 2021). "PRC1, TNS4, and CDKN3, which were used to construct the model, had significantly higher mRNA expression in lung adenocarcinoma samples than normal samples in the TCGA cohort." (PMID 40697537, 2025). "Furthermore, elevated TNS4 levels were detected in lung adenocarcinoma (LUAD) tissues, while in vitro TNS4 knockdown resulted in a decrease in both cell proliferation and migration." (PMID 40906372, 2025).
colorectal cancer (11 papers, 2019 to 2025). A primary or metastatic malignant neoplasm that affects the colon or rectum. "Through functional analysis, we have confirmed that TNS4 is significantly downregulated by cetuximab in a subset of colorectal cancer cell lines including KRAS activating mutations, suggesting that TNS4 may be one of the pharmacological targets of cetuximab." (PMID 31409052, 2019). "TNS4 also upregulates Src expression to facilitate colorectal cancer metastasis and depends on Ras/MAPK signaling for its activity." (PMID 39995671, 2025). "For instance, TNS4 facilitates migration, invasion, and epithelial–mesenchymal transition (EMT) in colorectal cancer cells, potentially through upregulation of integrin-linked kinase (ILK), FAK, and Src." (PMID 40906372, 2025). "Nuclear localization of TNS4 has been previously identified in colorectal cancer metastases, and it is likely that having undergone EMT, these metastases would express low E-cadherin." (PMID 36851390, 2023). "Nonetheless, we provide evidence to show that SMARCA4 promotes colorectal cancer cell proliferation by interacting with PRMT1 to activate TNS4 and EGFR transcription." (PMID 33853662, 2021). "Moreover, a mutant SMARCA4R enhances the SWI/SNF complex’s ATPase activity, facilitating chromatin remodeling, which reinforces EGFR and TNS4 transcriptional expression, promoting proliferation in colorectal cancer cells and patient-derived tumor organoids." (PMID 40906372, 2025). "Thus, hyperactivated Wnt signaling contributes to tumorigenesis, with TNS4 being upregulated and integrated into Wnt signaling to exert its oncogenic role in colorectal cancer." (PMID 40906372, 2025). "Additionally, SMARCA4 recruited by PRMT1-mediated H4R3me2a enhances EGFR signaling and TNS4 expression in colorectal cancer, with elevated PRMT1 or SMARCA4 levels positively correlating with increased EGFR and TNS4 expression and decreased overall survival." (PMID 40906372, 2025). "Our data suggest that LGR5, KCNN4, TNS4 and CENPH are correlated with radiation sensitivity of colorectal cancer cells, and the indicator composed by them can reflect the prognosis of colorectal cancer patients undergoing radiation therapy." (PMID 37328854, 2023). "Prognostic indicator based on TCGA colorectal cancer patients containing four key radiation resistance genes (LGR5, KCNN4, TNS4, CENPH) was established." (PMID 37328854, 2023). "Indeed, in colorectal cancer (CRC) cell lines, TNS4 has been shown to induce EMT by repressing E-cadherin at the post-transcriptional level and significantly increase migration and invasion." (PMID 36851390, 2023). "In conclusion, through the sorting and analysis of the radiation resistance projects in the GEO database and tumor vs. normal tissue project in TCGA-COREAD database, we established a gene panel (LGR5, KCNN4, TNS4 and CENPH) in colorectal cancer patients receiving radiotherapy." (PMID 37328854, 2023). "Furthermore, in colorectal cancer cells, the EGFR/Kras pathway specifically upregulates TNS4, though without affecting TNS3, and in HeLa cells, the EGFR-activated RAF/MEK/ERK pathway facilitates p300 binding to the TNS4 promoter, enhancing its expression." (PMID 40906372, 2025). "Collectively, these results reveal that the levels of TNS4 expression in LS174T, DLD1, DiFi, and WiDr cells are closely correlated with their oncogenic growth, suggesting that TNS4 may play a crucial role in regulating the oncogenic potential of a subset of colorectal cancer cells." (PMID 31409052, 2019).
lung carcinoma (9 papers, 2017 to 2025). "Aberrant expression of TNS4 has been reported in several cancers, including breast, colon, gastric, and lung cancers." (PMID 41226525, 2025). "TNS4 is a focal adhesion molecule that belongs to the tensin family, and it is significantly up-regulated in a variety of gastrointestinal tumors and lung cancer." (PMID 37328854, 2023). "In lung cancer, TNS4 was upregulated by EGF-mediated STAT3 activation and its aberrant expression increased cancer cell invasiveness." (PMID 31052206, 2019). "TNS4 is the member of the tensin family and has oncogenic activity in colon cancer, thymoma and lung cancer." (PMID 29283424, 2017). "TNS2 shows promise as a diagnostic adjunct for discriminating GISTs from other gastric sarcomas, while TNS1 and TNS4 are increasingly incorporated into validated multi-gene signatures predicting survival and therapeutic response in bladder, colorectal, gastric, and lung cancers." (PMID 40906372, 2025). "Compared with normal tissues, the expression of ADM2, CLIC6, KIF20A, LAD1, MUC5B, and TNS4 was up-regulated, and the expression of ATG16L2, KCNK3, MAFF, NKD1, and SPATA13 was down-regulated in lung cancer tissues." (PMID 34804921, 2021).
hepatocellular carcinoma (7 papers, 2017 to 2025). A malignant tumor that arises from hepatocytes. "Additionally, epidermal growth factor (EGF)-induced extracellular regulated protein kinase 1/2 (ERK1/2) upregulates TNS4, promoting proliferation and migration in hepatocellular carcinoma." (PMID 40906372, 2025). "Moreover, TNS4 expression was significantly increased in hepatocellular carcinoma and intrahepatic cholangiocarcinoma and was positively feedback-regulated by KRAS and SOX17 to stimulate migration and proliferation." (PMID 37328854, 2023). "This regulatory mechanism is corroborated in hepatocellular carcinoma (HCC) cells, where EGF-induced ERK1/2 activity drives TNS4 upregulation." (PMID 40906372, 2025).
colon carcinoma (6 papers, 2014 to 2025). "TNS4 was found to be highly expressed in colon cancer samples and cell lines, including SW480, SW620, and HT29." (PMID 40906372, 2025). "TNS1, TNS3 and TNS4 knockdown reduces the proliferation of several cancer cell lines, such as colon cancer and acute myeloid leukemia cell lines." (PMID 37510408, 2023). "The only report about the role of TNS4 in CRC carcinogenesis indicates that its upregulation promotes the tumorigenicity of colon cancer through β-catenin." (PMID 36158666, 2022). "Two other genes, TNS4 and CLDN2, which are known as clinical markers for colon cancer staging, also were upregulated in R cells." (PMID 24884630, 2014).
pancreatic cancer (5 papers, 2016 to 2026). "GMFG is transported into pancreatic cancer cells where it binds to intracellular tensin-4 (TNS4), promoting FAK/AKT phosphorylation and coordinating two programs critical for metastatic outgrowth: enhanced cell-ECM adhesion and increased de novo fatty acid synthesis." (PMID 42314060, 2026).
prostate carcinoma (5 papers, 2013 to 2025). A carcinoma that arises from epithelial cells of the prostate gland. "Conversely, in prostate cancer and related cell lines, TNS4 is downregulated and exhibits a context-specific function by downregulating EGFR expression, indicating a different role in this context." (PMID 40906372, 2025). "In contrast, TNS4 exhibits tumor-suppressor–like functions in breast and prostate cancers, where its downregulation promotes tumor growth and angiogenesis via the c-Cbl/β-catenin/VEGFA axis or disrupts normal growth-regulating pathways." (PMID 41439026, 2025). "Downregulation of both TNS4 and ΔNp63 correlates with prostate cancer progression from primary to metastatic disease." (PMID 40906372, 2025). "Despite its widespread oncogenicity, TNS4 exhibits an anti-tumorigenic function specifically in prostate cancer." (PMID 40906372, 2025). "Moreover, TNS4 negatively regulates EGFR expression in prostate cancer cells, contrasting with findings in other cancers." (PMID 40906372, 2025). "Although the basis for this tissue-specific difference remains unknown, EGFR inhibition likely mediates TNS4’s anti-tumorigenic function in prostate cancer." (PMID 40906372, 2025). "Furthermore, TNS4 is downregulated in paclitaxel-resistant PC-3 and DU145 prostate cancer cells, where its expression negatively correlates with EGFR levels, indicating that TNS4 exerts anti-tumor effects via EGFR inhibition." (PMID 40906372, 2025). "Similarly, TNS4 exhibits contradictory effects on EGFR: it stabilizes EGFR in lung/bladder/esophageal cancers but downregulates EGFR in prostate cancer cells." (PMID 40906372, 2025).
head and neck squamous cell carcinoma (4 papers, 2022 to 2025). A squamous cell carcinoma that arises from any of the following anatomic sites: lip and oral cavity, nasal cavity, paranasal sinuses, pharynx, larynx, and salivary glands. "The results indicated that ANXA8L1 (cholangiocarcinoma), PSMF1 (stomach adenocarcinoma) and TNS4 (head and neck squamous cell carcinoma, lung squamous cell carcinoma, rectum adenocarcinoma, stomach adenocarcinoma) were highly expressed in these cancers." (PMID 35807355, 2022).
breast carcinoma (3 papers, 2024 to 2025). "Paradoxically, TCGA and CPTAC databases show downregulated TNS4 mRNA across breast cancer subtypes (luminal, HER2+, triple-negative)." (PMID 40906372, 2025). "In breast cancer, for example, discordant observations of high TNS4 protein positivity versus low mRNA levels strongly suggest post-transcriptional regulation, emphasizing the necessity of multi-omics validation in biomarker studies." (PMID 40906372, 2025). "Collectively, these studies indicate that TNS4 promotes breast cancer progression." (PMID 40906372, 2025). "Furthermore, the opposing functional outcomes in MCF10A (pro-migratory) and MCF7 (anti-migratory) cells further indicate that TNS4’s role may be subtype-dependent, underscoring the need for subtype-specific investigations in breast cancer." (PMID 40906372, 2025).
lymph node metastasis (3 papers, 2017 to 2020). "Importantly, positive expression of TNS4 and VEGFA was significantly associated with lymph node metastasis, and short survival time of ESCC patients, respectively." (PMID 32732965, 2020).
adenoma (2 papers, 2020 to 2022). A neoplasm arising from the epithelium. "The exact contribution of TNS4 to adenoma development remains to be investigated, but the ApcMin/+ mouse represents a good model to study this." (PMID 32567731, 2020). "Apart from that, given the roles of TNS4 in cell mobility and migration, the hypomethylation of this gene in adenoma and cancer tissues implies that colorectal cells might tend to migrate in the very early stage of carcinogenesis, rather than after malignant transformation." (PMID 36158666, 2022). "Further analysis indicated that the changes in methylation levels of the four iRFE MDGs, ADHFE1-Cluster1, CNRIP1-Cluster1, MAFB, and TNS4, occurred in adenoma tissues, while changes did not occur until stage IV in cell-free DNA." (PMID 36158666, 2022). "Since aberrant activation of Wnt signalling promotes stemness and leads to the development of an adenoma (ie the first step in the development of CRC), we hypothesized that TNS4 could be a target of Wnt signalling and thereby mediate some of the stemness‐inducing activity of Wnt signalling." (PMID 32567731, 2020).
esophageal squamous cell carcinoma (2 papers, 2022 to 2023). Esophageal squamous cell carcinoma (ESCC) is a type of esophageal carcinoma (EC) that can affect any part of the esophagus, but is usually located in the upper or middle third. "In esophageal squamous cell carcinoma, miR-324-5p down-regulation is a prevalent change that stimulates cell division, migration, invasion, and tumor growth via triggering the EGFR-EFNA1/EPHA2-VEGFA signaling pathway by suppressing TNS4 expression." (PMID 36983713, 2023).
intrahepatic cholangiocarcinoma (2 papers, 2023 to 2025). A carcinoma that arises from the intrahepatic bile duct epithelium in any site of the intrahepatic biliary tree. "In intrahepatic cholangiocarcinoma (iCCA), SOX17 has been identified as a transcriptional regulator of TNS4, thereby facilitating tumor growth." (PMID 40858565, 2025).
esophageal cancer (1 paper, 2025). A primary or metastatic malignant neoplasm involving the esophagus. "Transitioning to esophageal cancer, TCGA data revealed TNS4 mRNA upregulation in ESCC tumors." (PMID 40906372, 2025).
gallbladder cancer (1 paper, 2025). "Additionally, it has been recently linked to gallbladder cancer metastasis through the GPRC5A, JAK2 (Janus kinase 2), STAT3 (signal transducer and activator of transcription 3), and TNS4 (tensin 4) signalling pathways." (PMID 40427604, 2025).
gastric adenoma (1 paper, 2024). A neoplastic polyp that arises from the stomach. "Elevated TNS4 expression has been shown to promote the EMT process through AKT/GSK-3β signaling and is proposed to correlate with the development and progression of gastric adenomas, a process purportedly triggered by Hp infection." (PMID 38542354, 2024).
glaucoma (1 paper, 2021). Increased pressure in the eyeball due to obstruction of the outflow of aqueous humor. "Finally, a GWAS study would be of interest to explore the potential role of Tns4 and Smarce1 as risk factors in human presentations of glaucoma, myopia, and/or keratoconus." (PMID 33634081, 2021). "This work motivates further study of Smarce1 and Tns4 for their role(s) in ocular pathology involving the corneoscleral envelope as well as the development of novel mouse models of ocular pathophysiology, such as myopia and glaucoma." (PMID 33634081, 2021).
inflammatory bowel disease (1 paper, 2023). A spectrum of small and large bowel inflammatory diseases of unknown etiology. "Among these genes, Dusp4, Epha2, Atp11a, and Tns4 are reported to be overexpressed in human CRC, while the expression of Thbs1 is increased in patients with inflammatory bowel disease." (PMID 37296911, 2023).
intestinal polyp (1 paper, 2020). Discrete abnormal tissue masses that protrude into the lumen of the intestine. "Overall, 135/148 (91.2%) of the total intestinal polyps were positive for TNS4 expression by IHC, whilst adjacent normal areas were negative." (PMID 32567731, 2020).
invasive breast carcinoma (1 paper, 2016). A carcinoma that infiltrates the breast parenchyma. "Moreover, TNS4 expression correlated with metastasis in invasive breast carcinomas." (PMID 27724925, 2016).
myopia (1 paper, 2021). "Additionally, Tns4 and Smarce1 signaling could be evaluated after form deprivation-induced myopia in wild type mice." (PMID 33634081, 2021).
parasitic infections (1 paper, 2025). "Meanwhile, genes related to cancer metastasis, such as Tns4, Neu1, Serpina10, and Trib3 (54, –, 57), as well as Mcpt1 and Mcpt2, which are associated with parasitic infections, were significantly upregulated after infection." (PMID 39727670, 2025).